CAT (catalase)
Diseases named in the same sentence as CAT in open-access papers (continued):
Sharing a sentence is not in itself a finding about the gene and the disease.
non-alcoholic fatty liver disease (6 papers, 2023 to 2025). "A previous study has evidenced significantly lower hepatic levels of SOD, catalase, and GPx and SOD activities in nonalcoholic fatty liver disease compared to serum levels of these enzymes, respectively." (PMID 36985557, 2023). "Various research studies have proven that the levels of antioxidants such as glutathione, catalase, and SOD are significantly lower in animals with non-alcoholic fatty liver disease (NAFLD)." (PMID 37108615, 2023). "Phenolic extract of M. citrifolia fruits significantly increases the activities of antioxidant enzymes to effectively attenuate oxidative stress in a high-fat diet-induced nonalcoholic fatty liver disease (NAFLD) mouse, such as glutathione (GSH) and catalase (CAT)." (PMID 40227265, 2025). "The neutral polysaccharide (CPP-1) could protect cells from oxidative damage (increasing the activity of SOD and CAT and reducing the MDA content), reduce the body fat index of nonalcoholic fatty liver disease mice, and improve the liver function." (PMID 39624060, 2024). "In a model of fructose-induced non-alcoholic fatty liver disease in rats, silymarin reduced lipid index parameters such as aspartate aminotransferase (AST), aspartate aminotransferase (ALT), superoxide dismutase/hydrogen peroxidase (SOD/CAT), and thiobarbituric acid reactive substances (TBARS)." (PMID 37570615, 2023).
non-alcoholic steatohepatitis (6 papers, 2021 to 2025). "Earlier studies have shown that FAK deficiency significantly suppresses MET/CAT-driven hepatocarcinogenesis, In DUSP22-deficient tumors, FAK activation promotes the progression of nonalcoholic steatohepatitis–associated HCC." (PMID 41232667, 2025). "For instance, NQO1 is up-regulated while CAT is down-regulated in nonalcoholic steatohepatitis livers." (PMID 35875696, 2022). "An antioxidant enzyme NAD(P)H quinone dehydrogenase 1 (NQO1) is up-regulated while CAT is down-regulated in nonalcoholic steatohepatitis livers." (PMID 35875696, 2022). "Interestingly, protein expression of CAT is decreased in samples from patients with non-alcoholic steatohepatitis (NASH)." (PMID 35883749, 2022).
pancreatitis (6 papers, 2018 to 2023). Inflammation of the pancreas. "Pancreatitis induction was characterized by reduction of the activity of CAT, SOD, and GPx in pancreas and lung, corroborating previous findings." (PMID 29861777, 2018). "Indeed, rutin reduced plasma levels of thiobarbituric acid reactive substances (TBARS), lipid peroxidation end by-products, and enhanced glutathione peroxidase (GPx), Superoxide dismutase (SOD), Catalase (CAT) activity in pancreatic tissue of alcohol and cerulein-induced pancreatitis model." (PMID 37743919, 2023). "In a mouse model of pancreatitis, oral administration of lysine also decreased the plasma concentration of IL-6, malonaldehyde, and nitric oxide, and increased the key antioxidant enzymes superoxide dismutase, catalase, and glutathione peroxidase in the pancreas." (PMID 34445459, 2021). "Carvacrol decreased pancreatitis‐induced MDA and 8‐OH‐dG levels, and the activities of the liver SOD, CAT, and GSH‐Px increased." (PMID 36348778, 2022). "Given its catalase and SOD mimetic property, scientists probed the anti-pancreatitis activity of nanoceria against a cerulein-induced murine model of acute pancreatitis by multiple biochemical studies." (PMID 33118404, 2020). "While various antioxidant enzymes depletion, including superoxide dismutase (SOD), catalase, and GSH, often occurred in pancreatitis, it is acknowledged that the replenishment of antioxidant agents, e.g. NAC, have been recognized as a feasible idea for acute pancreatitis therapy." (PMID 33118404, 2020).
pheochromocytoma (6 papers, 2014 to 2024). "An in vitro study showed that 1,8-cineole has a protective effect on oxidative stress induced by hydrogen peroxide (H2O2) in rat pheochromocytoma cells by enhancing the expression of CAT, SOD, and GPH-PX." (PMID 36139274, 2022). "We found lower serum activity of CAT only in patients with pheochromocytoma (-58%, p < 0.001) in comparison with the controls." (PMID 34239688, 2021). "Additionally, increased GSH-Px activity in pheochromocytoma patients with a concomitant decrease in CAT activity may indicate their compensatory action in inactivating hydrogen peroxide." (PMID 34239688, 2021). "Similarly, improvements in the intracellular glutathione pool and in the activity of catalase and SOD enzymes by pretreatment with OA have been reported in PC12 cells, a cell line derived from a pheochromocytoma of rat adrenal medulla, exposed to H2O2 and 1-methyl-4- phenylpyridinium." (PMID 31683841, 2019).
polycystic ovary syndrome (6 papers, 2019 to 2025). A disorder that manifests as multiple cysts on the ovaries. "Interestingly, granulosa cells of polycystic ovary patients display increased ROS levels as well as reduced catalase activity." (PMID 41275450, 2025). "Furthermore, experiments showed that in mice, PPARγ agonists exhibit a positive effect on ROS levels in polycystic ovary by enhancing the expression of catalase." (PMID 41275450, 2025). "In an animal study of polycystic ovary syndrome (PCOS), oral treatment with onion for 60 consecutive days increased levels of total antioxidant capacity (TAC), SOD and CAT and reduced MDA." (PMID 34567150, 2021). "A significant positive correlation was found between 25(OH)D with TAC and activities of SOD, GPx, and CAT in FF of women with healthy and polycystic ovaries, whereas, a significant negative correlation existed between 25(OH)D and ROS level in FF of both studied groups." (PMID 31423416, 2019).
renal failure (6 papers, 1998 to 2023). "Because of kidney failure, concentrations of renal antioxidant enzymes (SOD, CAT, GSH, and GPx) were significantly reduced, as was apoptotic DNA fragmentation." (PMID 36646729, 2023).
sickle cell disease (6 papers, 2020 to 2026). Sickle cell anemias are chronic hemolytic diseases that may induce three types of acute accidents: severe anemia, severe bacterial infections, and ischemic vasoocclusive accidents (VOA) caused by sickle-shaped red blood cells obstructing small blood vessels and capillaries. "Catalase activity was significantly higher (p<0.001) in sickle cell anaemia (SS) participants compared to AA and AS participants." (PMID 34394292, 2021). "Our aim was to evaluate the relationships between CAT, GPx, and Prx2, focusing on their role at the RBC membrane, in hereditary spherocytosis (HS), sickle cell disease (SCD), β-thalassemia (β-thal), and healthy individuals." (PMID 38929068, 2024).
squamous cell carcinoma (6 papers, 2012 to 2024). A carcinoma arising from squamous epithelial cells. "Intracellular GSH and catalase levels were significantly lower in bEnd.3 cells adapted to 5 kPa O2, consistent with our previous findings in airway epithelial cells and other studies in epidermoid carcinoma cells." (PMID 32949969, 2020). "According to findings of Oberley and Oberley on papillomas and squamous cell carcinoma, the SOD and CAT reduction leads to a pro-oxidant state of cells, facilitating tumorigenesis." (PMID 30978928, 2019). "We found that the activity of GSH-related enzymes was significantly higher in cancer tissues of both adenocarcinoma and squamous cell carcinoma than in the noncancerous tissues, while the activity of CAT was significantly higher in the adjacent noncancerous tissues than in the tumor tissues." (PMID 31781331, 2019). "Thus, in mice subjected to chemical induction of squamous cell carcinoma, the expression of catalase and GR was decreased only in HO-1+/− mice and was not affected in HO-1 knock-out animals." (PMID 23285041, 2012).
thyroid disorders (6 papers, 2017 to 2025). "Schizophrenics have susceptibility toward thyroid disorders, and the reduction in catalase (CAT) levels results in elevated hydrogen peroxide (H2O2) thereby playing a potential role in thyroid hormogenesis." (PMID 33995058, 2021). "The increase in serum SOD and CAT activities in some of the thyroid disorder groups indicated increased production of superoxide anion and hydrogen peroxide, respectively." (PMID 28584708, 2017). "The increased SOD and CAT activities could also be due to up-regulation in the synthesis of these enzymes as a result of the thyroid disorders, as protective response against oxidative stress." (PMID 28584708, 2017). "In addition, nucleotide alterations in genes encoding the antioxidant enzymes, superoxide dismutase (SOD), glutathione peroxidase (GPx), and catalase (CAT), were screened in order to assess the underlying genetic cause that may be linked to thyroid disorders." (PMID 28584708, 2017). "Monitoring the levels of SOD, CAT, GPx, and TAC in breast milk can provide insights into the oxidative status of mothers with GDM and thyroid disorders." (PMID 41228398, 2025). "Patients with thyroid disorders had significantly higher serum superoxide dismutase (SOD) and catalase (CAT) activities compared to control, but had lower activities in RBC." (PMID 28584708, 2017). "Amongst the four thyroid disorder groups, the FTA group showed lower CAT activities than control." (PMID 28584708, 2017). "Out of the four thyroid disorder groups, only MNG showed higher CAT activities than control." (PMID 28584708, 2017). "While CRM treatment alone ameliorated the altered activities of SOD and CAT in both the altered thyroid conditions, VIT-E alone could stabilize SOD and CAT in hyper-thyroid model only and failed to elicit any response in the hypo-thyroid model." (PMID 31092832, 2019).
tuberculosis (6 papers, 2014 to 2024). A chronic, recurrent infection caused by the bacterium Mycobacterium tuberculosis. "Isoniazid is a prodrug for tuberculosis that must be activated by the bacterial KatG catalase." (PMID 28106035, 2017). "In addition, they evaluated four mycobacterial media: Middlebrook 7H11 with additives and OADC (oleic acid, albumin, dextrose, and catalase) supplement A (7H11-A), Middlebrook 7H11 with another supplement trademark (7H11-B), tuberculosis blood agar (B83), and Stonebrink’s medium." (PMID 35889961, 2022). "In anti-tuberculosis drug-induced liver damage in rats, increased LPO levels and decreased SOD and CAT levels were found." (PMID 38911247, 2024). "M. tuberculosis clinical isolates with deletion of the katG gene, which is required for catalase-peroxidase activation of isoniazid, were reported previously for two MDR-TB isolates in Uganda." (PMID 29847567, 2018).
abscess (5 papers, 2010 to 2025). An inflammatory process characterized by the accumulation of pus within a newly formed tissue cavity which is the result of a bacterial, fungal, or parasitic infection or the presence of a foreign body. "The scars of mice almost disappeared in the treatment group of CAT–Ce6 NCs with an abscess healing rate of 95.5% after 11 d of treatment, showing greatly accelerated recovery and healing process of abscess." (PMID 40463499, 2025). "In summary, this study synthesized a Glu‐responsive gel loaded with Gox, CAT, Ce6, and NB to eradicate traumatic infectious drug‐resistant pathogens and promote the healing of refractory abscess." (PMID 40433786, 2025). "Conventional methods, including Gram staining, mannitol fermentation, hemolysis on blood agar, catalase testing, and coagulase production, identified and isolated S. aureus and CoNS from all abscesses." (PMID 39077454, 2024). "Based on culture on mannitol salt agar plates, Gram-staining technique, and the catalase test, S. aureus (n = 100) was isolated from different specimens (blood, wound, sputum, and abscess)." (PMID 37095436, 2023). "By employing the cascade reaction of Gox and CAT enzymes, in situ oxygen supply to abscess sites was accomplished, which not only enhanced the occurrence of photodynamic behavior in the hypoxic infection environment but also facilitated the wound healing of abscesses." (PMID 40433786, 2025). "Hematoxylin and eosin (H&E) staining results showed that the abscess tissues of mice in the groups of PBS, Ce6, CAT, and CAT-PVP were still in an inflammation phase with severe inflammatory cells and thickening of the epidermis." (PMID 40463499, 2025).
breast tumor (5 papers, 2011 to 2025). "Studies showed lower CAT activity was associated with increased breast tumor metastasis." (PMID 40821783, 2025). "This was further evident from inhibition of estrogen-induced breast tumor formation in the xenograft model by overexpression of the antioxidant enzyme, catalase or by co-treatment with a chemical antioxidant, Ebselen." (PMID 23437041, 2013). "This was evident from inhibition of estrogen-induced breast tumor formation in the xenograft model by both overexpression of catalase as well as by co-treatment with Ebselen." (PMID 23437041, 2013). "Breast tumor invasiveness in polyoma middle T (PyMT) transgenic mice positive or negative for mitochondrial targeted catalase (mCAT)." (PMID 21605372, 2011).
chronic lymphocytic leukemia (5 papers, 2010 to 2025). "In chronic lymphocytic leukemia cells, an imbalance between SOD2, which converts harmful superoxide radicals into H2O2, and catalase, responsible for decomposing H2O2, leads to excessive H2O2 accumulation." (PMID 41009046, 2025). "Reduced CAT activity was observed in just diagnosed patients and patients in both treatment groups suggesting a disturbance of the protective role of these enzymes against free radicals in ALL and chronic lymphocytic leukemia (CLL)." (PMID 25519934, 2014).
emphysema (5 papers, 2019 to 2025). "We assessed the SOD activity as well as the GSH and catalase levels in a PPE emphysema model to investigate the antioxidant effect of NYT." (PMID 36299904, 2022). "The protective effects of mate tea against CS-induced emphysema were demonstrated in mice, preserving elastic fibers and lung architecture as well as the GSH/GSSG redox sensor ratio and catalase activity." (PMID 36978796, 2023). "Furthermore, quercetin was effective in preventing emphysema in mice, canceling CS effects, and keeping redox parameters such as SOD and CAT activities as well as the GSH/GSSG ratio at baseline levels." (PMID 36978796, 2023).
esophageal cancer (5 papers, 2009 to 2023). A primary or metastatic malignant neoplasm involving the esophagus. "The downregulated expression of catalase induced by MLN4924 in human esophageal cancer cells was also related to inhibiting NF-κB/p65." (PMID 37186123, 2023). "In our study, we elucidates a novel mechanism of NF-κB/Catalase/ATF3 pathway in MLN4924-induced protective autophagy in esophageal cancer cells, which provides a sound rationale and molecular basis for combinational anti-ESCC therapy with knockdown ATF3 and neddylation inhibitor (e.g. MLN4924)." (PMID 32398095, 2020). "These preclinical findings indicated that NF-κB-Catalase-ROS-ATF3 axis served as a new protective autophagy mechanism in esophageal cancer upon MLN4924 treatment, which provided a rationale for combinational anti-ESCC therapy with dual inhibition of neddylation and autophagy pathways." (PMID 32398095, 2020). "In esophageal cancer cells, MLN4924 induces the expression of ATF3 by modulating NF-κB-Catalase-ROS pathway to trigger pro-survival autophagy, whereas targeting ATF3 blocks the autophagic response upon neddylation inhibition and thus sensitizes cancer cells to MLN4924-induced apoptosis." (PMID 32398095, 2020).
fetal growth restriction (5 papers, 2012 to 2022). A fetus that does not grow beyond the 10th percentile of conventionally accepted weight for gestational age. "Results showed that dietary supplementation with CAT significantly decreased the intrauterine growth restriction (IUGR) rate and increased the activity of serum CAT in neonatal piglets and umbilical cords (p < 0.05)." (PMID 35405818, 2022). "Moreover, toxic metals could modify the levels of antioxidant biomarkers, such as glutathione (GSH), superoxide dismutase (SOD), and catalase, leading to poor pregnancy outcomes, such as fetal growth restriction, pre-eclampsia, and PTB." (PMID 30832205, 2019). "Intrauterine growth-restricted (IUGR) infants had increased serum levels of both oxidant (lipid peroxidation and DNA damage) and antioxidant indices (superoxide dismutase, catalase, glutathione peroxidase)." (PMID 22848830, 2012). "In the context of this paradigm, we evaluated the markers of redox balance—MDA and 4-HNE for OS and GPx, and SOD, CAT, and GSH for the antioxidant system in the cord blood plasma of newborns diagnosed with fetal growth restriction (FGR)—by using polarography, spectrophotometry, and Western blotting." (PMID 36670868, 2022).
fibromyalgia (5 papers, 2018 to 2025). A chronic disorder of unknown etiology characterized by pain, stiffness, and tenderness in the muscles of neck, shoulders, back, hips, arms, and legs. "In people with fibromyalgia, alterations in the expression of catalase and glutathione peroxidase, both enzymes capable of converting H2O2 into H2O, have already been detected." (PMID 36140620, 2022). "Previous studies showed a lower catalase activity in blood in people with fibromyalgia than in healthy people." (PMID 36140620, 2022). "Indeed, Soliman, El-Olemy, Hassan, Shaker and Abdullah showed a higher catalase activity in the blood after exercise in people with fibromyalgia." (PMID 36140620, 2022). "Perhaps the reduction in the salivary flow, which occurs by inhibition of the PNS, did not promote the transfer of enzymes from the blood to the saliva, justifying similar salivary catalase activity before and after the fatigue exercise protocol in people with fibromyalgia." (PMID 36140620, 2022). "The application of a single moment of intense exercise in sedentary individuals with fibromyalgia could lead to a decrease in antioxidant capacity, with reduced activity of enzymes such as catalase, superoxide dismutase or enzymes involved in glutathione metabolism." (PMID 36140620, 2022). "One study, using a combined exercise training intervention over 12 weeks in women with fibromyalgia, found a reduction in plasma TBARS and an increase in serum levels of the antioxidant enzyme, catalase." (PMID 29596311, 2018). "Our study suggests that a higher α-amylase activity and an impaired HRV can be used as possible biomarkers of fibromyalgia, associated with a reduction in salivary flow without changes in HRV and catalase activity after a fatigue exercise protocol." (PMID 36140620, 2022). "The oxidants and antioxidants equilibrium is unbalanced in this pathology: increased lipid peroxidation was detected in rats subjected to fibromyalgia, while superoxide dismutase, nonprotein thiols and catalase were significantly decreased." (PMID 31817734, 2019).
Headache (5 papers, 2012 to 2024). Cephalgia, or pain sensed in various parts of the head, not confined to the area of distribution of any nerve. "In the literature, increased headache frequency is associated with elevated NO• levels, alongside reduced antioxidant defenses, evidenced by lower antioxidant capacity values and decreased serum levels of superoxide dismutase and catalase." (PMID 39336458, 2024). "It was also demonstrated that as the frequency of headache days increased, the level of NO and MDA as biomarkers of oxidative stress went up and the antioxidant defense (as shown by TEAC values, SOD, CAT serum levels) went down." (PMID 31837702, 2019). "Significant negative correlations between CoQ10 or catalase levels in BMCs and headache parameters were observed (r = −0.59, P<0.05; r = −0.68, P<0.05, respectively)." (PMID 22532869, 2012).